REEP6 (receptor accessory protein 6)
Description:
Required for correct function and survival of retinal photoreceptors. Required for retinal development (By similarity). In rod photoreceptors, facilitates stability and/or trafficking of guanylate cyclases and is required to maintain endoplasmic reticulum and mitochondrial homeostasis (By similarity). May play a role in clathrin-coated intracellular vesicle trafficking of proteins from the endoplasmic reticulum to the retinal rod plasma membrane (By similarity).
Synonyms: C19orf32; DP1L1; FLJ25383; Yip2f; TB1; REEP6.1; REEP6.2; RP77; TB2L1
Tractability: Antibody: UniProt predicts a signal peptide or a membrane-spanning region. PROTAC: its protein half-life has been measured.
Gene: Protein-coding gene on chromosome 19 (1,491,034 to 1,497,927, forward strand). Ensembl gene ENSG00000115255.
Subcellular location: Endoplasmic reticulum membrane; Cytoplasmic vesicle, clathrin-coated vesicle membrane
Subcellular location (Human Protein Atlas): Endoplasmic reticulum; Acrosome
Gene Ontology:
Molecular function: protein binding
Biological process: detection of light stimulus involved in visual perception; endoplasmic reticulum organization
Cellular component: endoplasmic reticulum; endoplasmic reticulum membrane; nucleus; photoreceptor inner segment; clathrin-coated vesicle membrane
Genetic constraint (gnomAD): Loss-of-function variants: 18 observed, 19.89 expected, observed/expected ratio (o/e) 0.91, 90% interval 0.62 to 1.34. The upper end of that interval is the gene's LOEUF score, 1.34, which puts it in group 5 of 6, group 1 being the genes least tolerant of losing a copy. Missense variants: 273 observed, 233.48 expected, observed/expected ratio (o/e) 1.17, 90% interval 1.06 to 1.29. Synonymous variants: 121 observed, 101.73 expected, observed/expected ratio (o/e) 1.19, 90% interval 1.02 to 1.38.
Gene-disease validity (ClinGen):
ClinGen rates the evidence that REEP6 causes each of these diseases.
inherited retinal dystrophy (autosomal recessive): Definitive. An instance of retinal degeneration that is caused by an inherited modification of the individual's genome.
Homologues: Orthologues: dog REEP6 (83% identical), chimpanzee REEP6 (83% identical), guinea pig REEP6 (79% identical), rat Reep6 (61% identical), macaque REEP6 (61% identical), tropical clawed frog reep6 (58% identical), zebrafish reep6 (58% identical), Caenorhabditis elegans yop-1 (41% identical), Caenorhabditis elegans F56B3.6 (35% identical), Caenorhabditis elegans T03F6.6 (34% identical), Drosophila melanogaster Reepl1 (17% identical), Caenorhabditis elegans W01D2.3 (15% identical). Paralogues in human: REEP5 (56% identical), REEP2 (26% identical), REEP4 (26% identical), REEP1 (25% identical), REEP3 (23% identical).
Diseases named in the same sentence as REEP6 in open-access papers:
REEP6 is named in the same sentence as 30 diseases in open-access papers, as found by Europe PMC text mining. Sharing a sentence is not in itself a finding about the gene and the disease. The quoted sentences say what the papers report.
retinal degeneration (5 papers, 2017 to 2023). Degeneration of the retina. "Previous studies demonstrated that loss of REEP6 in mouse and zebrafish (REEP6-/-) resulted in progressive retinal degeneration." (PMID 33917198, 2021). "The complete loss of REEP6 led to a faster retinal degeneration than we observed in the L135P homozygous knock-in model, suggesting that this missense mutation is potentially a hypomorphic allele." (PMID 28475715, 2017). "Moreover, we found transcriptional deregulation of two other genes, Reep6 and Fabp7, which have been linked directly to retinal degeneration." (PMID 35626712, 2022). "Collectively these data suggest that REEP6 plays a critical role in rod photoreceptor ER homoeostasis and trafficking of essential phototransduction proteins, loss of its function results in impairment of visual transduction processes leading to subsequent retinal degeneration." (PMID 28475715, 2017). "Interestingly, REEP6 gene therapy could rescue retinal degeneration in REEP6 mutant mice." (PMID 37238941, 2023). "Therefore, one of the verified missense mutants, which is known as REEP6.1, was integrated into the murine genome through CRISPR‐Cas9, inducing clinical manifestations of RP, such as retinal degeneration and the malfunction of rod photoreceptors." (PMID 35845351, 2022).
retinitis pigmentosa (4 papers, 2016 to 2024). Retinitis pigmentosa (RP) is an inherited retinal dystrophy leading to progressive loss of the photoreceptors and retinal pigment epithelium and resulting in blindness usually after several decades. "In addition, several mutations have been identified in the REEP6 gene that are linked to the development of an autosomal recessive disease called Retinitis pigmentosa." (PMID 35626712, 2022).
autosomal recessive retinitis pigmentosa (3 papers, 2016 to 2023). Autosomal recessive retinitis pigmentosa (RP) is an autosomally recessive inherited retinal dystrophy leading to progressive loss of the photoreceptors and retinal pigment epithelium and resulting in blindness usually after several decades. "REEP6 mutations cause autosomal-recessive retinitis pigmentosa, and three novel REEP6 variants have been found among ethnic Chinese." (PMID 37238941, 2023). "Ten causative variants in REEP6 associated with autosomal recessive retinitis pigmentosa have been reported, including five missense variants, two frameshift deletions, one duplication, one splicing variant, and one genomic rearrangement." (PMID 33917198, 2021). "Our data suggested that REEP6 c.268G>C may be a recurrent causative variant in Chinese autosomal recessive retinitis pigmentosa patients." (PMID 33917198, 2021).
lung carcinoma (3 papers, 2016 to 2023). "For example, REEP6 polymorphisms at positions 992 and 996 have been associated with colon cancer, and low levels of REEP6 are significantly correlated with reduced cell growth and invasion in lung cancer cells." (PMID 37238941, 2023). "The results clearly indicated that REEP5 and REEP6 were required for proper growth and migration of A549 lung cancer cells in vitro and in vivo." (PMID 27966653, 2016). "In A549 lung cancer cells, which endogenously express CXCR1, the depletion of REEP5 and REEP6 significantly reduced growth and invasion by downregulating IL-8-stimulated ERK phosphorylation, actin polymerization and the expression of genes related to metastasis." (PMID 27966653, 2016). "Interestingly, REEP5 and REEP6 activate interleukin-8 (IL-8)/CXC chemokine receptor 1 (CXCR1, a G-protein coupled receptor) signaling to promote tumor cell proliferation/migration, angiogenesis, and macrophages/neutrophils recruitment in the tumor microenvironment in lung cancer." (PMID 37238941, 2023).
Obesity (3 papers, 2022 to 2024). Accumulation of substantial excess body fat. "REEP6 also regulates adrenergic signal transduction in adipocytes, and its inactivation causes obesity-related metabolic dysfunction." (PMID 37238941, 2023). "Our data indicate a correlation between increased skeletal muscle REEP6 expression and diminished response to exercise in people with overweight and obesity." (PMID 37988600, 2024). "A protein of the same family as REEP5, i.e., REEP6, has been shown to be regulated by thermogenic stimuli in adipose tissue, and furthermore, REEP6 KO mice were defective in cold-induced thermogenesis, showing an obesity-prone phenotype." (PMID 36142750, 2022).
breast carcinoma (2 papers, 2016 to 2022). "Finally, based on co-expression network analysis, we screened 7 potential gene markers related to metabolic characteristic index, of which CLCA2, REEP6, SPDEF, and CRAT can be used to indicate breast cancer prognosis." (PMID 35875026, 2022).
retinal disease (2 papers, 2016 to 2017). "These factors resulting from loss of REEP6 could cumulatively contribute to the photoreceptor cell death phenotype, delineating the mechanisms of retinal disease pathology in Reep6 KO mice." (PMID 28475715, 2017).
Retinal dystrophy (2 papers, 2016 to 2020). Retinal dystrophy is an abnormality of the retina associated with a hereditary process. "We report biallelic mutations of REEP6 in seven affected individuals from five families with retinal dystrophy." (PMID 27889058, 2016). "In addition, recent studies demonstrate that genetic mutations in REEP6 are responsible for causing retinitis pigmentosa, an inherited retinal dystrophy characterized by loss of photoreceptors in the retina." (PMID 32075961, 2020). "Mutations in REEP6 have not been implicated in any human disease previously, and these data show that mutations in REEP6 can cause inherited retinal dystrophy." (PMID 27889058, 2016). "Therefore, our study implicates REEP6 in retinal homeostasis and highlights a pathway previously uncharacterized in retinal dystrophy." (PMID 27889058, 2016).
colon cancer (1 paper, 2023). "Although it was reported that REEP6 plays a role in lung and colon cancers, its clinical impact and biological role in TSCC are still unknown." (PMID 37238941, 2023).
glioma (1 paper, 2022). A benign or malignant brain and spinal cord tumor that arises from glial cells (astrocytes, oligodendrocytes, ependymal cells). "In addition, we explored the proteins expressed by REEP6, LARP4B, CWC27, GOLGA2, ATP6AP1 and ERO1B in glioma patients through the HPA database, and REEP6, LARP4B, GOLGA2 and ATP6AP1 showed higher staining intensity in glioma than in normal brain tissue." (PMID 36552760, 2022).
Insulin resistance (1 paper, 2024). Increased resistance towards insulin, that is, diminished effectiveness of insulin in reducing blood glucose levels. "Reep6 knockout in mice results in reduced protein kinase A–mediated signaling and mitochondrial mass in brown AT, as well as exacerbated high-fat diet–induced insulin resistance and inflammation in AT, suggesting a role in metabolism regulation." (PMID 37988600, 2024).
oral cancer (1 paper, 2023). "Moreover, we used another cohort of oral cancer patient from the TCGA database to investigate the association of REEP6 expression with the prognosis of patients." (PMID 37238941, 2023). "Thus, we focused on analyzing the TCGA database for the REEP6 gene expression and its association with prognosis in oral cancer patients in the study." (PMID 37238941, 2023). "We have shown that the high expression level of REEP6 is positively correlated with poor DFS in oral cancer patients, implying that REEP6 plays a role in drug resistance." (PMID 37238941, 2023). "Higher REEP6 expression was related to shorter disease-free survival (DFS) in oral cancer patients with poorly differentiated tumor cells." (PMID 37238941, 2023). "A high co-expression of REEP6/epithelial–mesenchymal transition or cancer stemness markers also resulted in poor DFS in oral cancer patients." (PMID 37238941, 2023). "The clinical impact of REEP6 expression and gene co-expression on prognosis were analyzed in oral cancer patients including TSCC patients from The Cancer Genome Atlas database." (PMID 37238941, 2023). "Second, REEP6 contributes to the migration of TSCC cells, and oral cancer patients with an elevated co-expression of REEP6/Slug also had poor DFS." (PMID 37238941, 2023). "Third, REEP6 promotes drug resistance in TSCC cells, and oral cancer patients with an elevated co-expression of cancer stemness markers (CD166, ABCG2, ALDHA1) also had poor DFS." (PMID 37238941, 2023). "Moreover, a high co-expression of REEP6/CD166 (AHR = 2.28, 95%CI = 1.10–4.75, p = 0.027), REEP6/ABCG2 (AHR = 3.65, 95%CI = 1.42–9.41, p = 0.007) and REEP6/ALDH1A1 (AHR = 3.25, 95%CI = 1.34–7.90, p = 0.009) was related to the DFS of oral cancer patients in the TCGA database." (PMID 37238941, 2023).
retinitis pigmentosa 77 (1 paper, 2021). Any retinitis pigmentosa in which the cause of the disease is a mutation in the REEP6 gene. "Retinitis pigmentosa 77 is caused by mutations of REEP6 (MIM: 609346), which encodes a protein for the development of photoreceptors." (PMID 33917198, 2021).
Rod-cone dystrophy (1 paper, 2023). An inherited retinal disease subtype in which the rod photoreceptors appear to be more severely affected than the cone photoreceptors. "In addition, REEP6 with a novel nonsense variant was found to be associated with a sporadic rod-cone dystrophy case." (PMID 37238941, 2023).
Usher syndrome (1 paper, 2021). A syndromic diseae characterized by the association of sensorineural deafness (usually congenital) with retinitis pigmentosa and progressive vision loss. "In our IRD database, the frequency of this variant is 0.015 in 165 samples including a homozygous REEP6 in an Usher syndrome patient." (PMID 33917198, 2021).
tumor (3 papers, 2016 to 2023). "This study compares REEP6 expression between normal and tumor tissues and investigates the association of REEP6 expression with clinicopathological outcomes in TSCC patients." (PMID 37238941, 2023). "Moreover, REEP6 might also regulate LITAF for inducing cancer growth/invasion or switching tumor associated-inflammation." (PMID 37238941, 2023). "We also compared the REEP6 expression between tumor adjacent normal and tumor tissues in TSCC patients." (PMID 37238941, 2023). "We found that the REEP6 expression was significantly increased in tumor tissues compared with that in normal tissues." (PMID 37238941, 2023). "Tumor tissues had higher levels of REEP6 compared to normal tissues in TSCC patients." (PMID 37238941, 2023). "According to our data, we probably could demonstrate the relative protein levels of REEP6 between normal and tumor tissues in TSCC patients." (PMID 37238941, 2023). "Moreover, REEP6 expression in tumor adjacent normal tissues of TSCC patients was significantly higher than that in normal tissues." (PMID 37238941, 2023). "To assess the clinical significance of REEP6 in TSCC, we initially evaluated the expression levels of the REEP6 protein between normal and tumor tissues of TSCC patients by IHC using a numerical scale for scoring intensity." (PMID 37238941, 2023). "First, we found significantly higher expression levels of REEP6 in tumor tissues of TSCC patients, and REEP6 promotes the cell growth of TSCC cells, implying that REEP6 might be involved in the tumorigenesis of TSCC." (PMID 37238941, 2023). "Statistical analysis revealed that tumor growth was remarkably reduced in the mice lacking both REEP5 and REEP6." (PMID 27966653, 2016).
retinopathies (2 papers, 2017 to 2025). "As an example, Reep6 plays a critical role in trafficking guanylate cyclases in rod photoreceptors, and its loss results in retinopathies 44,45." (PMID 40568109, 2025).
cancer (1 paper, 2023). A tumor composed of atypical neoplastic, often pleomorphic cells that invade other tissues. "Our study indicates that REEP6 is involved in the cancer malignancy of TSCC and has potential value as a diagnostic/prognostic biomarker and therapeutic target for TSCC patients." (PMID 37238941, 2023). "Previous studies showed that the IL-8/CXCR1 axis could increase properties of cancer stemness, indicating that the involvement of REEP6 in the drug resistance of TSCC might be associated with the IL-8/CXCR1 axis." (PMID 37238941, 2023). "Gene knockdown was used to evaluate the effects of REEP6 in cancer malignancy (colony/tumorsphere formation, cell cycle regulation, migration, drug resistance and cancer stemness) of TSCC cells." (PMID 37238941, 2023). "REEP6-knocked-down TSCC cells showed diminished colony/tumorsphere formation, and they also caused G1 arrest and decreased migration, drug resistance and cancer stemness." (PMID 37238941, 2023). "A few studies have examined the potential roles of REEP6 in various types of cancer." (PMID 37238941, 2023). "However, the role of REEP6 in cancers, especially in TSCC, is still unclear." (PMID 37238941, 2023). "We also analyze the biological role of REEP6 in TSCC cells, including cellular growth/migration and drug resistance/cancer stemness." (PMID 37238941, 2023). "Nevertheless, our study showed that REEP6 might regulate cell proliferation and drug resistance along with the expression of EMT and cancer stemness markers in TSCC cells." (PMID 37238941, 2023).
kidney disorder (1 paper, 2021). A disease involving the kidney. "Since the proband presented only RP without kidney disorders, the biallelic variants in REEP6 was the only candidate RP-associated variants." (PMID 33917198, 2021).
REEP6 also shares sentences with these, for which no sentence is quoted: achromatopsia (1 paper); cervical cancer (1); head and neck squamous cell carcinoma (1); hereditary spastic paraplegia (1); Leber congenital amaurosis (1); lymph node metastasis (1); macular degeneration (1); major depression disorder (1); neuroblastoma (1); Stargardt disease (1); thyroid cancer (1).